ALB (albumin)
Diseases named in the same sentence as ALB in open-access papers (continued):
Sharing a sentence is not in itself a finding about the gene and the disease.
Hypoalbuminemia (continued). "In cirrhosis-related sepsis, albumin demonstrates potential for managing hypotension and offering short-term survival benefits, particularly in SA-AKI where hypoalbuminemia is prevalent." (PMID 38139434, 2023). "Serum albumin was lower in the AKI group compared to controls and hypoalbuminemia remained an independent predictor of incident AKI." (PMID 36127479, 2023). "Hypoalbuminemia in cats can be found in various conditions such as FIP, tumors, and chronic diseases; however, it is possible to have normal or low albumin levels in cats with FIP." (PMID 37235153, 2023). "The higher urinary albumin excretion in the AKI group is an unlikely explanation for this finding, as the level of albuminuria was well below of what would lead to hypoalbuminemia." (PMID 36127479, 2023). "Since then, HSA infusions have been commonly used in the neonatal ICU for volume expansion, inflammatory disorders, increased capillary permeability, hypoalbuminemia, indirect hyperbilirubinemia, and protein-losing conditions." (PMID 37888650, 2023). "Although there is no clear explanation for this result, it is possible that anemia and hypoalbuminemia progress slowly in IBD patients, allowing them to adapt to low levels of hemoglobin and albumin and, thus, to develop tolerance to their fatigue." (PMID 37176558, 2023). "Suppressed albumin synthesis is partly due to the activation of cytokines such as IL-1, IL-6, and TNF-α, a common observation in cancer, resulting in hypoalbuminemia." (PMID 37492594, 2023). "Furthermore, to further confirm the effect of albumin infusions in hypoalbuminemia patients who were grouped based on whether they had albumin infusions, PSM was conducted according to the serum albumin value and the disease severity to make sure that the two groups were comparable." (PMID 37277756, 2023). "Phase angle and s-albumin, together with additional biochemical nutritional and inflammatory parameters (i.e., s-CRP, IL-6), may help to monitor and adjust dry body weight in wasted HD patients, since hypoalbuminemia is also caused by hemodilution during states of chronic volume expansion." (PMID 35458220, 2022). "This study was based on clinical observations in the inpatient internal medicine wards and some previous studies, leading us to hypothesize that patients with hypoalbuminemia do worse than those with normal serum albumin, regardless of the underlying diseases or comorbidities." (PMID 35268297, 2022). "Therefore, the cause of low albumin (e.g., cachexia) rather than the hypoalbuminemia itself could be seen as the cause for the poor outcome." (PMID 35052870, 2022). "Low albumin levels in equine were previously thought to be associated with liver disease and/or liver failure, but a retrospective study of literature data concluded that consistently low albumin levels (hypoalbuminemia) reported were not directly associated with severe liver disease." (PMID 36230267, 2022). "The uniqueness of the current study is its evaluation of albumin upon admission as a long-term prognostic indicator in hospitalized patients also after discharge from the medicine wards, and its examination of patients without hypoalbuminemia-associated disorders (HAD)." (PMID 35268297, 2022). "Severe proteinuria and hypoalbuminemia were noted in early porcine-NHP xenotransplants, necessitating frequent administration of intravenous albumin to maintain protein balance in an appropriate range." (PMID 35757701, 2022). "One of the factors that lowers the AGR is the decrease in ALB, and it has been reported that factors related to coagulation such as fibrinogen, factor V, and factor VIII fluctuate in hypoalbuminemia." (PMID 35853032, 2022). "Patients with hypoalbuminemia had a higher ASA grade and Charlson Comorbidity Index, as well as a lower hemoglobin value and prothrombin time compared to those with normal albumin values and low BMI." (PMID 36363567, 2022).
Hypoalbuminemia (continued). "Based on the serum albumin level at the initiation of CRRT, we categorized the patients into initial normoalbuminemia (serum albumin ≥ 3.0 g/dL) and initial hypoalbuminemia (serum albumin < 3.0 g/dL) groups." (PMID 35672868, 2022). "The biochemical test showed that the levels of total protein (TP), albumin, and globulin were significantly increased in the RSGB treatment group, which indicated that RSGB treatment improved hypoproteinemia and hypoalbuminemia in thyrotoxicosis mice." (PMID 36389720, 2022). "This corresponds to a previous study of 70 dogs with CE where hypoalbuminemia was shown to be associated with negative outcomes, as well as a previous study of 165 dogs with CE where non-survivors showed significantly lower serum albumin levels compared to survivors." (PMID 35739843, 2022). "The levels of Total protein (TP), Albumin (ALB), and Globulin (Glb) were significantly decreased, which indicated that excessive thyroxine induced hypoproteinemia or hypoalbuminemia." (PMID 35720307, 2022). "Human serum albumin (HSA) has been widely used for volume expansion and correcting hypoalbuminemia in critical care for nearly 70 years worldwide." (PMID 35721190, 2022). "Hypoalbuminemia may be a non-specific risk indicator for later-stage PAH since serum ALB plays a role in multiple physiological and pathological processes related to PAH progression, including hepatic dysfunction, starvation, and systemic inflammatory processes." (PMID 35722097, 2022). "Moreover, CHE was diagnosed based on the NPT recommended by the Japanese Society of Hepatology, and the cutoff values for serum ammonia and albumin levels were adopted with reference to the predetermined thresholds for hyperammonemia and hypoalbuminemia; however, these may also need to be verified." (PMID 36449492, 2022). "Patients with elevated CRP levels > 10 mg/L and normal albumin are classified as mGPS-1, and patients with elevated CRP and hypoalbuminaemia (< 35 g/L), are classified as mGPS-216." (PMID 35739171, 2022). "The patients with HAD who actually had hypoalbuminemia (n = 736) were of similar age and had a similar CCI and 1 yr readmission rate as those with HAD and normal serum albumin (n = 1265)." (PMID 35268297, 2022). "Previous investigations have found that hypoalbuminemia is common in HFRS; some cohorts have exhibited a close correlation between serum albumin level and both disease severity and mortality." (PMID 35265645, 2022). "The antioxidative and other non-oncotic properties of albumin may be of critical importance in antimicrobial defense and injury repair mechanisms, and more significant hypoalbuminemia can therefore have systemic effects and cause collateral damage to vital organ systems." (PMID 33925831, 2021). "However, since the relationship between albumin levels and dialysis patient outcomes is controversial with only a few relevant studies; therefore, this study aimed to investigate the relationship between hypoalbuminemia and prognosis in patients with critical AKI under CRRT." (PMID 34496793, 2021). "MAL piglets in this model were noted to have significantly greater albumin concentrations than REF piglets, whereas hypoalbuminemia is often observed in children with SAM." (PMID 34134040, 2021). "However, this dosage could potentially increase the probability of toxicity in severe renal dysfunction stages, even more pronounced when associated with low ALB levels, and could also increase the risk of lack of efficacy in patients with hypoalbuminemia." (PMID 33672057, 2021). "In addition, GA cannot be transferred to renal tubular epithelial cells because the most of GA is bound to albumin in the blood, but during hypoalbuminemia, the concentration of free GA may increases and transport into tubular cells by passive diffusion to inhibit 11βHSD2." (PMID 33481180, 2021).
Hypoalbuminemia (continued). "Branched-chain amino acids (BCAAs) are provided to cirrhotic patients for relieving the hypoalbuminemia, and the oral BCAA supplementation has also alleviated the oxidized shift of serum ALB." (PMID 33804859, 2021). "Although hypoalbuminemia is suggested as a pivotal marker for the pathology of many infections (reviewed very recently in Wiedermann, 2021) including in COVID-19, albumin damage has not been directly implicated in infectious disease to the best of our knowledge." (PMID 34821549, 2021). "We found lower albumin levels in patients with low FXIII activity, in agreement with previous studies that demonstrated hypoalbuminemia in severe COVID-19 patients." (PMID 34736472, 2021). "Parallel to its response as an acute phase reactant, hypoalbuminemia in COVID-19 may reflect a dysregulated immune response in the early stages of the disease, which could lead to increased capillary permeability and the release of albumin into the interstitium." (PMID 34441957, 2021). "In patients with hypoalbuminemia, the PTA of efficacy and safety were reduced due to an increased V, highlighting the influence of ALB on amikacin dosing optimization with a larger impact than eGFR." (PMID 33672057, 2021). "The mean serum albumin level of pregnant women in the RDS group was 33.38 ± 3.31 g/L, and 6 cases (10.71%) had hypoalbuminemia." (PMID 34485188, 2021). "There is evidence implying that serum zinc concentration is reduced by hypoalbuminemia in CKD patients, as zinc is bound to albumin in the circulation." (PMID 34631763, 2021). "Another study investigated the prognostic role of serum ALB in patients with advanced HNSCC who underwent surgery and flap reconstruction and determined that preoperative hypoalbuminemia was a poor prognostic indicator in this population." (PMID 34539891, 2021). "The therapeutic use of human albumin solution (HAS) in critically ill or surgical patients and to correct hypoalbuminemia has been studied for decades." (PMID 33925831, 2021). "In our study, serum albumin had a significant correlation with PMI, indicating that PMI has an important role in protein malnutrition state represented by hypoalbuminemia." (PMID 34064607, 2021). "In conclusion, consecutive hypoalbuminemia is a simple and effective adverse prognostic factor in patients with DLBCL, which reminds us to pay more attention to patients with low serum albumin at EoT during follow-up." (PMID 33585232, 2020). "The administration of albumin and a high-casein diet also increased the tissue expression of EGFR, ERK1, ERK2, TGF-β, and collagen and decreased that of MMP-8 relative to the hypoalbuminemia control (P < 0.05)." (PMID 32518615, 2020). "The inflammatory cytokines also induce a reduction of serum albumin as CRP production is prioritized, and the kinetics promote exacerbated hypoalbuminemia when patients fail to intake required nutrition in disorders such as cachexia." (PMID 32567660, 2020). "Thus, the lack of vitamin D's immunomodulation actually may result in hypoalbuminemia, independent of urinary loss of albumin." (PMID 33026128, 2020). "Despite the fact that most of our patients had severe hypoalbuminemia, we detected VTE even in patients with only a modest reduction in serum albumin (3 g/dL)." (PMID 32438633, 2020). "Hypoalbuminemia and elevated AST levels were often observed in critical patients, and the correlation of albumin and AST levels with disease severity was also found." (PMID 33521010, 2020). "Also the fact that we did not study serum albumin levels in these children yet edema in these children has now been found to cause hypoalbuminemia which is linked to mortality could have affected our outcomes." (PMID 32589637, 2020). "In our study, 72.30% of the patients developed hypoalbuminemia after THA, and 19.72% of the patients met the criteria and received albumin supplementation." (PMID 33170383, 2020).
Hypoalbuminemia (continued). "Hypoalbuminemia which appeared in OB might be due to the switching of the synthesized protein in the liver, during the inflammation, towards increasing the synthesis of the positive acute phase proteins which is concomitant with a decrease in the albumin production." (PMID 31955661, 2020). "Serum albumin was measured within 1 h after ROSC, and hypoalbuminemia was defined as admission serum albumin <3.5 g/dl." (PMID 31565439, 2019). "Therefore, an interesting hypothesis would be whether the administration of albumin in patients with acute pancreatitis and hypoalbuminemia could decrease mortality or prevent development of SAP, since severe acute pancreatitis shares many features with sepsis syndrome and septic shock." (PMID 31068202, 2019). "However, this does not suggest that a low serum albumin level is not an important risk factor, but means that hypotension due to hypoalbuminemia may be difficult to control using pressor approaches." (PMID 30833633, 2019). "As intravenous use of albumin has been shown not to decrease mortality in the critically ill, further studies are needed to determine if there are any other therapeutic options that would specifically target the worse prognosis associated with hypoalbuminemia in cardiogenic shock." (PMID 31095609, 2019). "While there is greater medical risk and increased mortality in undernourished dialysis patients, particularly those with hypoalbuminemia, the patients in our study on OWHD-DT had acceptable levels of serum albumin even compared with the DOPPS patients." (PMID 29954331, 2018). "Several researches have revealed that the occurrence of decreased serum ALB levels, namely hypoalbuminemia, is secondary to the elevation of serum CRP, as many cancer patients with hypoalbuminemia already have high concentrations of serum CRP." (PMID 29568406, 2018). "Thrombocytopenia, anemia, hypoalbuminemia, increase in ALKP, decreased albumin and globulin ratio were the most common findings in diagnosing canine ehrlichiosis." (PMID 28344412, 2017). "However, a total of 14 patients (1.2 %) required further treatment for hypoalbuminemia; all received high-protein enteral supplements and pancreatic enzymes (Kreon®-Abbott, Germany) 10,000–25,000 IU with each meal during at least 3 to 6 months; 2 were readmitted and managed with IV albumin." (PMID 27783366, 2017). "Albumin serum levels were only decreased in AOA1 being significantly lower than in the AOA2 and AT groups, while hypoalbuminemia had Sp of 95.5% for AOA1 relative to AOA2 or AT patients." (PMID 29127364, 2017). "Because PNI is calculated by serum albumin and lymphocyte count, decreased PNI represents hypoalbuminemia and decreased lymphocyte count, both responsible for worse outcomes in cancer patients." (PMID 28578683, 2017). "The present study evaluated the impact of albumin oxidation on measurements of COP in proteinuric patients with various degrees of systemic inflammation and of hypoalbuminemia." (PMID 27453993, 2016). "This study highlights the possibly misleading decrease in albumin concentrations, when measured by BCG, which complicates the interpretation of hypoalbuminemia in epidemiological and clinical studies." (PMID 27453993, 2016). "According to the mGPS, 31 (18.5%) patients had both hypoalbuminemia and high CRP levels (mGPS = 2), 77 (16.4%) patients had high CRP levels but normal albumin (mGPS = 1), and the remaining 360 (76.9%) patients had neither risk factor (mGPS = 0)." (PMID 26390126, 2015). "Vitamin D deficiency is very common among hospitalized adult tuberculosis patients in Uganda especially in patients with hypoalbuminemia, anemia, HIV co-infected patients with CD4 count <200cells/mm3 and hypocalcemia corrected for serum albumin levels." (PMID 23886009, 2013).
Hypoalbuminemia (continued). "Due to chronic inflammation, uremia, loss of amino acids, restrictive diets or anorexia, and albumin synthesis may be insufficient to compensate for enhanced catabolic rate, and damage imposed by XOD-derived oxidants would probably enhance its breakdown, leading overtime to evident hypoalbuminemia." (PMID 23819009, 2013). "Vitamin D deficiency was noted to be more common among patients with hypocalcaemia corrected for albumin concentration (67%), HIV co-infection (82.6%), CD4 counts < 200 cells/μl (83.2%), anemia (86.1%) and hypoalbuminemia (97.4%)." (PMID 23886009, 2013). "Due to an interaction between serum albumin and MELD, the impact of hypoalbuminemia fell as the MELD score increased." (PMID 23349678, 2013). "The patients with hypoalbuminemia had a shorter median ESRD-free survival of 122 months, compared to 145 months for those with normal albumin levels [HR = 2.45, 95% CI 1.48–4.07]." (PMID 22719981, 2012). "A study done to evaluate if CRP and serum albumin were survival predictors of esophageal cancer demonstrated that only serum CRP concentration and hypoalbuminemia were independent prognostic indicators of survival." (PMID 21176210, 2010). "Hypoalbuminemia is common in ICU-admitted AHF patients, and while albumin supplementation remains debated, some evidence suggests it may reduce short-term mortality in specific subpopulations." (PMID 41517774, 2026). "Mild hypoalbuminemia was present, but no proteinuria was detected (urinary albumin 10.1 mg/day and urinary creatin 0.8 g/day), suggesting a non-renal cause of hypoalbuminemia." (PMID 41476905, 2026). "Serum albumin, one of the PNI components, exerts anti-inflammatory and antioxidant effects; thus, hypoalbuminemia, reflecting both inflammation and inadequate protein intake, may predispose to oxidative stress–induced atrial injury." (PMID 41598492, 2026). "Albumin was not included in our final model, but it should be noted that our cohort did not include many patients with significant hypoalbuminemia, and no participants had severe liver disease, so the model should not be extrapolated to these groups." (PMID 41277849, 2026). "Patients with pCCA more often had low albumin, and hypoalbuminemia alone was not prognostic in this subgroup." (PMID 41504962, 2026). "In the CTEPH cohort, serum albumin and eGFR showed negative correlations with LOS, indicating that hypoalbuminemia and reduced renal function were linked to prolonged hospitalization in this subgroup." (PMID 40941614, 2025). "The mean serum albumin and globulin levels were 3.9 ± 0.5 g/dL and 2.8 ± 0.4 g/dL, respectively, with hypoalbuminemia observed in two patients (7.7%) and no abnormalities in globulin levels." (PMID 40755691, 2025). "This contrasts with smaller studies that reported significant outcome differences with hypoalbuminemia in non-traumatic care, as well as with composite indices where albumin plays a part." (PMID 41226896, 2025). "However, haemoglobin levels were significantly lower in the hypoalbuminemia group (126 g/L, IQR: 111-143) compared to the normal albumin group (142 g/L, IQR: 132-153), with a p-value<0.001, indicating statistical significance." (PMID 40161084, 2025). "We did not observe clinical problems (e.g., intradialytic hemodynamic instability) due to hypoalbuminemia and, therefore, do not recommend the routine use of albumin infusion." (PMID 41303814, 2025). "NS: nephrotic-range proteinuria and either hypoalbuminemia (serum albumin < 30 g/L) or edema when serum albumin is not available." (PMID 40802032, 2025). "Additionally, lower albumin levels were observed in patients with HRP, consistent with prior studies linking hypoalbuminemia to adverse cardiovascular outcomes." (PMID 40283491, 2025). "Given the rarity of SCARs with docetaxel use and the lack of guidance on hypoalbuminemia, we present a case of docetaxel-induced erythema multiforme in a patient with low albumin levels." (PMID 41209896, 2025).